TIMP1 (TIMP metallopeptidase inhibitor 1)
Diseases named in the same sentence as TIMP1 in open-access papers (continued):
Sharing a sentence is not in itself a finding about the gene and the disease.
pulmonary fibrosis (continued). "IL-33 promotes hepatic and pulmonary fibrosis by suppressing MMP-9 expression and enhancing TIMP1 expression, thereby creating an imbalance between MMPs and TIMP1." (PMID 40356603, 2025). "Systemic miR-26a KO enhances PTEN expression and suppresses the fibrosis-promoting molecule TIMP-1 by inhibiting the PI3K/Akt-mTOR pathway, thereby attenuating pulmonary fibrosis, as summarized in graphical abstract." (PMID 41323794, 2025). "To characterize the kinetic effects of 2 U/kg i.t. bleomycin on various biochemical markers of lung fibrosis, we measured the concentrations of TGFβ1, IL6, TNFα, IL1β, CINC1, WISP1, VEGF, and TIMP1 in BALF at days 3, 7, and 14 following instillation." (PMID 38534359, 2024). "The authors stated that the imbalance between MMP-9 and TIMP-1 can determine ARDS development and the tendency to pulmonary fibrosis." (PMID 37545954, 2023). "In the clinical study of pulmonary fibrosis, an abnormal MMP-9/TIMP-1 ratio indicates a dysfunctional matrix degradation system, which leads to the progress of pulmonary fibrosis." (PMID 35402615, 2022). "In this study, we aim to investigate the in vivo and in vitro roles of GSK-3 inhibition in the modulation of MMP-9 and MMP-2 and of their inhibitors TIMP-1 and TIMP-2 in the development of lung fibrosis." (PMID 34235177, 2021). "In the lung, CCR2+ M-MDSCs stimulate lung fibroblasts to release tissue inhibitor of metalloproteinase 1 (TIMP1) by producing TGF-β, which promotes lung fibrosis." (PMID 30792719, 2019). "Increases in the expression of TIMP-1, an inhibitor of MMP-9, lead to the resolution of pulmonary fibrosis." (PMID 29311918, 2017). "To evaluate the anti-inflammatory and anti-fibrotic effects of CNP against BLM-induced lung fibrosis in periostin-CNP Tg mice, we analyzed the mRNA expression changes of IL-1β, IL-6, bFGF, TGF-β, TIMP1, and collagen 1A." (PMID 26895702, 2016). "In contrast, other studies have demonstrated that the exogenous NO donor, DETA/NO (125–500 μM; t1/2 ~20 h), promoted TIMP-1, TGF-β1 and collagen synthesis in fibrosis-related disorders such as keloid (hypertrophic scar) and pulmonary fibrosis." (PMID 27065874, 2016). "APN treatment significantly decreased the lung fibrosis scores, protein and mRNA expression of pulmonary TGF-β1, CTGF and α-SMA content, and blood MMP-9 and TIMP-1 in a dose-dependent manner (p<0.05)." (PMID 25945502, 2015). "If MMP‐9 is decreased and TIMP‐1 is increased in lung tissue, it promotes ECM accumulation leading to pulmonary fibrosis." (PMID 26660549, 2015). "Previous studies have reported that DBT can reduce bleomycin-induced pulmonary fibrosis in rats by boosting matrix metalloproteinases, MMP-1, MMP-9, and TIMP-1 expression." (PMID 25861366, 2015). "TIMP-1 and TIMP-2 are expressed by a variety of cell types, and are known to play a major role in regulating pulmonary fibrosis." (PMID 22911824, 2012). "While TIMP-1 appears to play a significant role in the mechanism by which miR-26a KO mice exhibited milder pulmonary fibrosis than WT mice, Timp1 does not contain a direct target sequence for miR-26a." (PMID 41323794, 2025). "Additionally, treatment with UGRP1 protein significantly promoted the pulmonary fibrosis of young mice, as shown by the increased Masson staining, Ashcroft score, tissue levels of HYP and expression levels of Col1a1, Timp1 and α-SMA." (PMID 36934284, 2023). "BLM-induced pulmonary fibrosis was significantly prevented in CCL6-neutralized aged mice, as shown by the decreased Masson staining and Ashcroft score, reduced tissue levels of HYP, and reduced expression levels of Col1a1, Timp1, and α-SMA." (PMID 36934284, 2023). "Furthermore, ELISA was used to detect pulmonary fibrosis markers COL-1, COL-3, WNT, Vimentin, β-Catenin, Fibronectin, α-SMA, N-Cadherin, E-Cadherin, TWIST, CTGF, FGF2, PDGF-α, MMP2, MMP8, MMP9, MMP13, TIMP1, TGF-β, Smad2, and Smad3 expression levels." (PMID 37812357, 2023).
pulmonary fibrosis (continued). "It has been identified that Timp1 stimulates fibroblasts activation and proliferation via the interaction of CD63/integrin β1, and the activation of the intracellular ERK pathway in the development of lung fibrosis." (PMID 33777519, 2021). "Following bleomycin-induced lung injury, Il11−/− mice are protected from pulmonary fibrosis and exhibit lesser ERK, STAT3 and NF-kB activation, reduced Il1b, Timp1, Ccl2 and diminished IL6 expression, both at baseline and after injury: placing Il11 activity upstream of IL6 in this model." (PMID 34239012, 2021). "TIMP1−/− mice have not been shown to develop reduced lung fibrosis in response to bleomycin; however, our finding of augmented levels of human TIMP1 suggests an unsuccessful attempt at regulating fibrosis in IPF." (PMID 32171287, 2020). "To evaluate the anti-inflammatory and anti-fibrotic effects of CNP in BLM-induced lung fibrosis, we analyzed mRNA expression changes of pro-inflammatory cytokines (IL-1β and IL-6), pro-fibrotic cytokines and proteins (bFGF, TGF-β, TIMP1, and collagen 1A), and GC-B in the lungs." (PMID 26895702, 2016). "Moreover, increased MMP-9 expression preceded increased TIMP-1 expression, the former peaking on day 3, and the latter peaking on day 7, a pattern that supports the notion an imbalance between matrix degradation and its inhibition may contribute to PQ-induced pulmonary fibrosis." (PMID 25945502, 2015). "It was thought that the MMP-9/TIMP-1 ratio could indicate whether pulmonary fibrosis would be involved in ARDS or not." (PMID 37545954, 2023). "In this study, BLCN-induced pulmonary fibrosis was indicated after calculating the fibrosis score, immunohistochemical examination of the expression of ACTA2, the gene expression level of col1a1, hydroxyproline lung content, and the protein expression levels of TIMP-1 and PDGF-BB." (PMID 37631038, 2023). "It has been reported that an imbalance between MMP9 and TIMP1 plays a pivotal role in the pathogenesis of ARDS mainly through participating in airway remodeling, thus indicating the function of the MMP9/TIMP1 ratio in the evolution of pulmonary fibrosis in ARDS." (PMID 32969837, 2020). "For the pulmonary fibrosis evaluation, the fibrosis index calculated based on MT staining, collagen deposition and active TGF-β1 expression detected by ELISA, and the expression of TGF-β1, α-smooth muscle actin (SMA), fibronectin, MMP-9, and TIMP-1 by western blotting." (PMID 29311918, 2017). "The study results showed the mRNA level of TIMP-1 was not consistent with the reports, one possible explanation may be associated with the disorders of MMPs/TIMP-1 in lung fibrosis." (PMID 27191651, 2016). "Lastly, the concomitant increase in the gene transcripts of protease inhibitors, TIMP1, TIMP3, and SERPINE1, suggest that CaSR may facilitate a profibrotic environment promoting a non-degrading collagen-rich ECM, which is a defining feature of human and animal models of lung fibrosis." (PMID 40305220, 2025). "In conclusion, our data showed that plasma levels of TIMP-1 in COVID-19 patients correlated with the severity of the disease as well as with inflammatory markers and the chest CT score, suggesting that TIMP-1 could serve as a non-invasive biomarker for prognosis and lung fibrosis in COVID-19." (PMID 37509076, 2023).
melanoma (75 papers, 1999 to 2025). A malignant, usually aggressive tumor composed of atypical, neoplastic melanocytes. "Dysregulation of TIMP1 is associated with cancer progression and the accumulation of cancer associated macrophages and poor prognosis in high-risk surgically resected melanoma patients." (PMID 41226668, 2025). "In tumors such as gastric, pancreatic, colorectal, breast, melanoma, and thyroid cancer, TIMP1 is often significantly associated with poor prognosis." (PMID 40224547, 2025). "Spatial transcriptomic analysis of a national melanoma cohort revealed that TIMP1 expression in immune compartments associates with an HLA-A/MHC-I peptide loading signature in lymph nodes." (PMID 38777826, 2024). "In the current study, we found that in two melanoma cell lines, A2058 and A375, uPA, TIMP-1, MMP-2 and MMP-9 were associated with cell migration and invasion." (PMID 30042328, 2018). "Previous data from our laboratory showed increased Timp1 expression along melanoma progression and more important the assembly of a supramolecular complex containing Timp1, CD63, and β1-integrins associated with a more aggressive phenotype." (PMID 28430130, 2017). "In the present study, we have investigated the mechanisms underlying Timp1 role in melanoma progression." (PMID 28430130, 2017). "High TIMP1 expression is associated with poor prognosis in melanoma, where it can bind to CD63 and β1 integrin, inducing PI3-kinase pathway and cell survival." (PMID 28430130, 2017). "In contrast, high circulating TIMP-1 promotes subcutaneous B16 melanoma growth in association with increased angiogenesis, whilst suppressing metastatic lung colonisation." (PMID 24473089, 2014). "In this context, CD63, a member of the tetraspanin family, was first identified as an antigen associated with early stages of human melanoma and as a binding partner of TIMP1 on the cell surface." (PMID 23522389, 2013). "Paradoxically, elevated TIMP1 expression has been consistently linked to unfavorable prognoses across various cancers, including breast, lung, endometrial, pancreatic, and skin cancers, including melanoma and UVM." (PMID 40362553, 2025). "Using NanoString GeoMX, we found TIMP1 expression in the immune compartment of the TME, which corresponded to higher immunogenicity in lymph nodes (LN) due to its association with MHC-I peptide loading, indicating TIMP-1’s possible impact on melanoma immunogenicity through DC priming." (PMID 38777826, 2024). "From these results we conclude that an altered responsiveness of gelatinase B and TIMP-1 to induction by similar agents is associated with disease progression in human melanoma and that this altered responsiveness can have consequences to the aggressive nature of the disease." (PMID 10408860, 1999). "TIMP1’s involvement in anoikis resistance has been documented in melanoma cells, where it enabled survival and growth under suspension conditions." (PMID 40427104, 2025). "Except for S100B, the serum concentration of TIMP-1 is perceived as another promising biomarker in melanoma 58,59." (PMID 40535809, 2025). "In the GDC-TCGA-SKCM melanoma dataset, TIMP1 expression correlated with better survival, increased CD8 + T-cell infiltration, and expression of pivotal HLA genes." (PMID 38777826, 2024). "Recombinant TIMP-1 conjugated to glycosylphosphatidylinositol (TIMP-1-GPI) when combined with sublethal hyperthermic treatment demonstrated efficacy against melanoma cell lines 624.38-MEL, 93.04A12MEL, SK-MEL23, WM115, and WM266-4 under in vitro conditions." (PMID 39594665, 2024). "MMP-2 and MMP-9 are overexpressed in melanoma cells and positively correlated with highly metastatic tumor behavior, while their endogenous inhibitors, TIMP-1 and -2, are down-regulated in melanoma cells, exhibiting aggressive potential." (PMID 38247872, 2024).
melanoma (continued). "The strengths of this study include solid clinical evidence on the association of TIMP-1 with HLA expression and improved CD8 T cell levels, both in the tumor and in LN of melanoma patients." (PMID 38777826, 2024). "Using a reverse translational approach, we initially assessed the prognostication power of TIMP1 in comparison with CD8A in the GDC-TCGA-SKCM melanoma dataset, a cornerstone model for ICT research." (PMID 38777826, 2024). "Both TIMP-1 immunohistochemistry staining and serological TIMP-1 levels have prognostic values in lung, melanoma, breast, colon, and several other cancers." (PMID 37500057, 2023). "The suppression of Timp1 inhibited melanoma growth and lung colonization, as well as reduced resistance to dacarbazine." (PMID 36675165, 2023). "TIMP2 is thought to block the Wnt/catenin pathway, which is supposed to inhibit the proliferation of melanoma cells, although the function of TIMP1 on carcinogenesis is less clear." (PMID 36975387, 2023). "Previous data from our laboratory have also shown that TIMP-1 associates with CD63 and β1-integrin to form a supramolecular complex on melanoma cell surface (4C11- and 4C11+ melanoma cell lines)." (PMID 34502227, 2021). "Compared with healthy individuals, patients with stage I–III melanoma have higher median serum TIMP-1 levels, influencing overall and DFS." (PMID 35003391, 2021). "In this study, it was confirmed that these melanoma cells use the TIMP1/CD63/β1-integrin complex to induce the activation of signaling pathways involving NF-κB and ERK precisely to promote resistance to Vemurafenib." (PMID 34502227, 2021). "The most recent study demonstrated that Vemurafenib-resistant melanoma cells (Mel28 and A375 cell lines) also form the TIMP1/CD63/β1-integrin supramolecular complex." (PMID 34502227, 2021). "We observed high levels of proteolytically active MMP-9 concurrently with very low levels of melanoma-derived TIMP-1 at the time of collagen IV dissolution, exclusively when melanoma cells were integrated into SR and expressed Tspan8." (PMID 32455575, 2020). "MMP-9 and MMP-3 were mainly expressed by keratinocytes whereas TIMP-1 was mainly expressed by Tspan8+ melanoma cells." (PMID 32455575, 2020). "We previously showed that the host deletion of ADAM9 leads to enhanced growth of grafted B16F1 melanoma cells by a mechanism mediated by TIMP1 and the TNF-α/sTNFR1 pathway." (PMID 32906814, 2020). "TIMP-1-overexpressing melanoma cells showed elevated anchorage-independent growth in soft agar and increased tumorigenesis and lung metastasis in vivo." (PMID 30486830, 2018). "Increased serum level of TIMP-1 was correlated with an unfavorable prognosis in patient with advanced stage melanoma." (PMID 30486830, 2018). "Melanoma cells overexpressing TIMP-1 had increased anchorage-independent growth and in vivo cancer progression." (PMID 30486830, 2018). "Similar findings have appeared also in patients with malignant melanoma, for whom high TIMP-1 indicated impaired disease-free survival, and in head and neck squamous cell carcinoma patients who had shorter disease-free survival." (PMID 29929486, 2018). "Melanoma-CM also influenced the expression of matrix genes as well as genes encoding proteins that impact on matrix remodelling, such as MMP2 and TIMP1." (PMID 29545604, 2018). "In the present study, we demonstrated that the signal transduction pathways in bornyl cis-4-hydroxycinnamate-treated melanoma cells involve up-regulation of TIMP-1 and TIMP-2 proteins and down-regulation of uPA protein." (PMID 30042328, 2018). "Elevated levels of serum MMP-8, MMP-9, and TIMP-1 have appeared in several cancers: lung, gastric, hepatocellular, and colorectal, but also in melanoma and head and neck cancer." (PMID 29929486, 2018). "We determined signaling pathways activated by Timp1 in cell lines corresponding to different phases of melanoma progression, performing a genetic approach using transfection assays to inhibit Timp1 gene expression." (PMID 28430130, 2017).
melanoma (continued). "Using a melanoma progression model, we evaluated the impact of Timp1 and AKT silencing, as well as PI3K, PDK1, and protein kinase C (PKC) inhibitors on aggressiveness characteristics." (PMID 28430130, 2017). "Here we provide evidence for the mechanisms by which Timp1 contributes to melanoma progression through increasing cell survival." (PMID 28430130, 2017). "This study brings new insights about the mechanisms by which Timp1 promotes cell survival in melanoma, and points to novel perspectives for therapeutic approaches." (PMID 28430130, 2017). "As previously demonstrated, Timp1 overexpression confers an anoikis-resistant phenotype to both the murine melan-a melanocyte lineage and melanoma cell lines." (PMID 28430130, 2017). "In our model, increased sensitivity to dacarbazine was observed in melanoma cells silenced for Timp1." (PMID 28430130, 2017). "In our model, we demonstrated a progressive increase in Timp1 expression along the melanoma progression." (PMID 28430130, 2017). "We observed a decreased PDK1 activation in pre-malignant 4C cell line and in melanoma cell lines 4C11− and 4C11+ silenced for Timp1." (PMID 28430130, 2017). "Our laboratory has shown that the increase in Timp1 expression provides greater efficiency in metastases development, indicating a correlation between levels of Timp1 and a worse prognosis for melanoma." (PMID 28430130, 2017). "Here, we demonstrated that PKC activation in early phases of melanoma genesis requires TIMP1 and it is critical to favor cell survival." (PMID 28430130, 2017). "Previous work using a melanocyte malignant transformation model established by our group showed that increased expression of Timp1 along melanoma progression is correlated with anoikis resistance and malignant potential." (PMID 28430130, 2017). "We showed that PDK1Ser241 and PKCβIISer660 are activated by Timp1 in different stages of melanoma progression, contributing to colony formation and anoikis resistance." (PMID 28430130, 2017). "The half-maximal inhibitory concentration (IC50) of dacarbazine was determined in melanoma cells silenced for Timp1." (PMID 28430130, 2017). "The mechanisms associated with AKT activation independently of PI3K stimulation by TIMP1 in melanoma cells are under investigation." (PMID 28430130, 2017). "An increase in TIMP-1 mRNA levels induced by 5-Aza treatment has also been observed in melanoma and gestational tissues, indicating that promoter methylation mediates the expression of TIMP-1 in various cell types." (PMID 27130446, 2016). "Among the most interesting, highly and significantly over-expressed genes in metastatic primary melanomas were TIMP1, VCAN, SPP1, and CTHRC1, all of which are expressed both by stromal fibroblasts and melanoma cells (data not shown)." (PMID 26918341, 2016). "The biomarker signature consisting of TNFR-II, TGF-α, TIMP-1 and CRP is significantly prognostic of survival in patients with high-risk melanoma and warrants further investigation." (PMID 24457057, 2014). "In patients with melanoma, levels of TIMP-1 were found to be significantly higher in patients with unresected stage IV disease than in patients with resected stage I/II." (PMID 24457057, 2014). "Previously, we reported increased Timp1 expression along melanoma genesis and a tight correlation between Timp1 expression and its promoter methylation during melanocytes malignant transformation." (PMID 23522389, 2013). "In human melanoma cell lines, in which TIMP1 and beta-1 integrin were also found to be interacting, TIMP1 and CD63 levels together was shown to correlate significantly with colony formation capacity." (PMID 23522389, 2013). "Previous studies showed that TIMP1 was overexpressed in both liver and peritoneal metastases from patients with colorectal adenocarcinoma, melanoma and malignant thyroid neoplasms." (PMID 23548070, 2013). "In our melanoma model, both increase in Timp1 expression and anoikis resistance are acquired along tumor progression." (PMID 23522389, 2013).